CD163 (CD163 molecule)
Diseases named in the same sentence as CD163 in open-access papers (continued):
Sharing a sentence is not in itself a finding about the gene and the disease.
cancer (continued). "ER expression in cancer cells appeared higher in CD163-negative tumors compared to CD163-positive tumors, but this difference was not statistically significant (p = 0.22)." (PMID 30915533, 2019). "However, M2 macrophage markers (CD163 and CD206) were advanced and M1 macrophage marker (CD86) was suppressed in THP-1 cells after co-culture with the cancer cells transfected with antago-miR-34a compared with scramble-miR transfectant." (PMID 30885232, 2019). "In addition, some studies also evaluated the correlation between the ratio of CD163- to CD68-positive macrophages and clinicopathological features in malignant tumors." (PMID 31528210, 2019). "The association between high co-expression and co-localization of MMP-9/CD163/CD68 and poor survival in ER+ cancers suggests that these cancers may be candidates for macrophage-targeted therapies." (PMID 30558648, 2018). "When CD163-positive macrophages were evaluated in non-involved or control areas that were distant and free from the presence of cancer cells, all cases were negative (p < 0.01)." (PMID 30211114, 2018). "High expression of CD163 protein in TAMs was associated with improved OS in ER− cases (cohort A, P = 0.03 and TNBC cohort B, P = 0.04, respectively) but not in ER+ cancers." (PMID 30558648, 2018). "While unexposed monocytes have low expression of PDL1, CD163, and CD206 (black solid lines), exposure to mf, similar to those of cancer cell lines, significantly upregulate the cell surface expression of PDL1 (inhibitory), PDL2 (M2/inhibitory), CD206 (M2), and VCAM-1(M1)." (PMID 29668679, 2018). "No major alterations were found between the levels of the pro-inflammatory TNF, IL6, CCL2 and CCL5 and of the anti-inflammatory CD163 in macrophages cultured in the presence of cancer cells, with or without radiation exposure." (PMID 27513864, 2016). "CD68 and CD163 expression was not confined to the infiltrating TAMs, but also detected in cancer cells." (PMID 26769084, 2016). "We further confirmed a strong positive correlation between NLRC4 expression with myeloid lineage markers from the TCGA data set, including specific macrophage marker CD163 and common myeloid markers CD68 and CD33, suggestive of a myeloid origin of NLRC4 in human cancer." (PMID 27708283, 2016). "To determine whether the expression of Bmi1 in cancer cells correlates with the levels of TAMs, we examined Bmi1, CD68, and CD163 expression in gastrointestinal cancer tissues using IHC." (PMID 24312366, 2013). "In addition, as previous reports suggested, the production of CCL18 is correlated with the severities of several malignant tumors, and one of the potential producers of CCL18 is CD163+ macrophages." (PMID 24489574, 2013). "For the purposes of the microarray data validation, we have selected 9 genes that may play the most important role in cancer cells-macrophages interactions: CCL2, CCL3, CD163, CSF1R, HIF1, Il-18, MMP9, VEGF-C, and Wnt7b." (PMID 22353646, 2012). "TAMs displayed strong staining for NADPH oxidase NOX2, CD163 and CD 68 which clearly contrasted with cancer cells that were entirely negative for each of these markers." (PMID 21811634, 2011). "In addition, considerable infiltration of CD163+ TAMs and SIRPα+ TAMs were observed in the stroma surrounding the hypoxic cancer cell islets but not in the normoxic regions." (PMID 38183060, 2024). "However, abundant CD163 staining cannot rule out cancer recurrence if areas of Olig2+ nuclear atypia with notable Ki67 positivity are present." (PMID 38049893, 2023). "However, neither CD163 nor CD204 further increased significantly in the investigated cancer samples when compared to high-grade dysplasia." (PMID 37190121, 2023). "We first examined the correlations among all CD163+ TAM-related spatial metrics, including count and proportion of CD163+ TAMs, cancer-to-CD163+ NND-based metrics, and metrics of CD163+ TAM proximity to cancer cells (average numbers of adjacent or communicating CD163+ TAMs)." (PMID 35053472, 2022).
cancer (continued). "Furthermore, we also used multiplex immunofluorescence staining to verify the co-expression of CD147 with macrophages (CD68) and M2 macrophages (CD163) in these cancers, which CD68 was marked red, CD163 was marked green, CD147 was marked purple, and DAPI was marked blue." (PMID 35464411, 2022). "Among CD68+CD163+ TAMs also expressing the recently identified TREM2 marker, we could identify a CXCL10+IRF1+STAT1+ M1-type Mφ population (Cluster 9) shared between all cancer types." (PMID 34220848, 2021). "In addition to evaluating PDL1 expression on macrophages, we assessed expression on CD163-negative cells, the vast majority of which appeared to be cancer cells." (PMID 33352957, 2020). "Indeed, CD163 or CD68 macrophages in the stroma rather than in the cancer cell nests have been shown to correlate with a poor prognosis." (PMID 33149188, 2020). "Because macrophages are well-known to be fusogenic and several studies showed that macrophages could fuse with cancer cells in in vitro and in vivo animal studies, macrophage markers, such as CD14, CD45 and CD163, have primarily been used for the search of TN-hybrid cells in human tumors." (PMID 30736482, 2019). "Thus, CD163 is a very promising target for imaging of M2 macrophages but there is a lack of cancer specific evaluation and validation." (PMID 31695797, 2019). "CD163-positive macrophages within cancer cell nests or in the immediate adjacent stroma were evaluated at high power and compared to macrophages in normal or non-involved or control areas distant from cancer cell sites." (PMID 30211114, 2018). "In order to uncover that whether the Nrf2 activation of cancer cells correlated with CD163-positive macrophages stimulation or not, we stimulated cancer cells with CM of TEM or M0 macrophages in vitro." (PMID 30180849, 2018). "Interestingly we observed two cancer groups with regards to the frequencies of CD163+/CD206+ pixels, independent of cancer type." (PMID 30619287, 2018). "Notably, cancer cells also express the macrophages antigen CD68 and CD163." (PMID 26769084, 2016). "In addition, the COX-2+ cells in the cancer tissue sections accounted for 3%-13% of all the observed M1 TAMs (i.e., CD68+ HLA-DR+ or CD68+ iNOS+ cells), and accounted for 93%-100% of the M2 TAMs observed (CD68+ CD163+ or CD68+ VEGF+)." (PMID 24324582, 2013). "Interestingly, among pan-cancer, LGG showed the most significant correlation between GLA with CD86 (P=4.52e-27), CSF1R (P=8.17e-09),CCL2 (P=3.98e-14), CD68 (P=2.37e-34), IL10 (P=3.29e-21), IRF5 (P=8.5e-25), CD163 (P=3.8e-26), VSIG4 (P=9.17e-16) and MS4A4A (P=1.39e-21)." (PMID 37057282, 2023). "Our results suggest an association between CD163-expression in cancer cells and poor response to radiotherapy, as patients with CD163-positive tumors had significantly shorter DFS following postoperative radiotherapy as compared with those with CD163-negative tumors." (PMID 29725763, 2018). "Among them, many international cohorts of cancer patients have shown negative prognostic value for TAMs expressing CD68, CD163, CD204, CD206, MARCO, and stabilin-1." (PMID 39516356, 2024). "Although no data regarding CD163 expression in IOPN exist in the literature, this marker has already been indicated as a poor prognostic moderator in different cancer types including PDAC." (PMID 37086293, 2023). "The mRNA expression level of CD163 and ARG1 clearly decreased in cancer patients under chemotherapy regardless of the presence of bevacizumab, although bevacizumab accelerated the decrease of ARG1." (PMID 26840567, 2016). "In a follow-up study it was shown that MCF-7 cancer cells obtained CD163 (and CD45) expression through hybridization of the cancer cells and macrophages, rather than in vitro paracrine cellular interaction." (PMID 27136533, 2016). "The MCF-7 cancer cells clearly expressed GFP, but neither CD45 nor CD163 despite repeated transwell chamber system experiments." (PMID 26585897, 2015).
cancer (continued). "In cancer tissue samples with negative/weak or moderate expression of TGM2 in GC cells, 20.0% (1/5) and 37.5% (9/24) of the samples, respectively, showed high expression of the macrophage marker CD163." (PMID 32467608, 2020). "The basal expression of selected cell surface markers (M1, M2, inhibitory) on either human monocytes or cancer cell lines suggest that human monocytes do not express PDL2 (M2/inhibitory), VCAM-1 (M1), CD206 (M2), and have a low expression of PDL1 (M1/inhibitory) and CD163 (M2) (black lines)." (PMID 29668679, 2018).
infection (280 papers, 2007 to 2025). The state of being infected such as from the introduction of a foreign agent such as serum, vaccine, antigenic substance or organism. "In the present study, we found that treating PAMs and PPMs prior to PRRSV inoculation significantly reduced the frequency of PRRSV+ cells, clearly indicating that their susceptibility to infection depends on CD163 expression." (PMID 39723134, 2024). "With the development of gene editing technology, several edited versions of the CD163 gene in pigs have been developed and shown to confer complete resistance to infection caused by PRRS viruses." (PMID 38544785, 2024). "Previous studies have implicated porcine CD163 in macrophage activation delay upon infection with virulent G. parasuis strains, while its exact roles in sensing G. parasuis infection have not yet been assessed." (PMID 36977274, 2023). "Proteomic analysis showed that the expression levels of FCGR2A and CD163 were higher in these patients than in patients with infection-associated HLH." (PMID 37653176, 2023). "PAM cell lines that stably express CD163, an M2 macrophage marker, are highly susceptible to infection by both the PRRSV-1 Lelystad strain and PRRSV-2 VR-2332 strain." (PMID 36992483, 2023). "Specifically, 3D4 cell lines designated 3D4CD163, 3D4CD163−6E8-mutant, and 3D4CD163−9A10-mutant were generated via infection with recombinant lentiviruses encoding porcine full-length CD163, CD163–6E8-mutant and CD163–9A10-mutant, respectively." (PMID 33050150, 2020). "Infection with both strains was associated with reduced fetal brain weight and increased number of placental CD163-positive cells, as well as elevated in utero interferon alpha and cortisol levels." (PMID 31340725, 2019). "Our study also included two markers in the CD163 gene, which encodes the membrane receptor used by the virus to enter macrophages and initiate infection." (PMID 31374992, 2019). "CD163 is associated with alternatively-polarized macrophages, and macrophage polarization plays a significant role in immunity and infection." (PMID 30650570, 2019). "Recent in vivo challenge experiments of pigs in which both copies of the CD163 gene had been knocked out using gene-editing technology confirmed that CD163 is required for infection by PRRSV-2 and highly pathogenic PRRSV-2 (HP-PRRSV)." (PMID 29925651, 2018). "The previously identified susceptibility bio-marker CD163 appears to have only played a secondary role in the observed infection dynamics." (PMID 27770812, 2016). "CD163 protein expression is closely regulated and associated with the innate immune response to infection." (PMID 24597777, 2014). "A PRRSV susceptible cell line expressing two major receptors for infection in macrophages, namely Sn and CD163, was constructed." (PMID 20587060, 2010). "Infection was associated with an increase in the expression of CD163 in brain, kidney and lung." (PMID 38389522, 2024). "In other controlled and conditioned trials and in experimental infections, some single nucleotide polymorphisms markers (SNPs) on different exons of the CD163 gene were investigated to elucidate those related to susceptibility, resistance, or “resilience” profiles in relation to PRRSV infection." (PMID 37570285, 2023). "The infection in macrophages and the enigmatic CD14+CD163+ cells with the pathogenic Alfort-187 strain at 36 h post-infection might bias a pro-inflammatory environment, which could prevent an efficient T cell stimulation." (PMID 34445493, 2021). "Alternatively, as these are important to the viral replication cycle in the host and can change the availability and function of the receptor CD163, animals with greater concentration of SMs on their cell surfaces may be more susceptible to infection." (PMID 33363202, 2020).
infection (continued). "Beyond showing that multiple gene edits can be combined in a livestock animal to achieve simultaneous resistance to two major viruses, our study introduces a valuable model for investigating infection mechanisms of porcine pathogenic viruses that exploit pAPN or CD163 for entry." (PMID 32876563, 2020). "In addition to CD163, cellular proteases, such as the aspartic protease cathepsin E and trypsin-like serine proteases, have been implicated in the uncoating process and subsequent infection." (PMID 33918746, 2021). "Plasma haptoglobin levels have been found to rise rapidly in mice infected with T. congolense and this increase was the most sensitive marker of infection, the very early decline in CD163 expression could cause a reduction in haptoglobin uptake and the observed increase in plasma concentration." (PMID 19365556, 2009). "Subsequent trials conducted by this research team further established that these maternal CD163 gene-edited pigs can protect their fetuses from infection with PRRSV." (PMID 40065264, 2025). "Semi-quantitative analysis showed that caspase-1 and CD163 double-positive signals were significantly increased in the infected group at the early infection when compared with the control group." (PMID 40143222, 2025). "Although CD163 is the proposed receptor for both PRRSV-1 and PRRSV-2, these viruses exploit different sites on CD163 to establish infection." (PMID 39943192, 2025). "Further analysis revealed that PAMs pretreated with E. coli 166 showed upregulation of NF-κB and downregulation of CD163 at different time points post-infection, whereas PAMs only infected with ASFV exhibited the opposite trend." (PMID 40008879, 2025). "There were also differences in the slopes of the simple linear regression lines between other proteins (IL-18, C3, IL-10, and CD163) and time post infection that further highlighted the dissimilarity between Cov and nLongC immune recovery (Figure A1)." (PMID 41369364, 2025). "The up-regulation of CCR7 and down-regulation of CD163 explain the enhanced immune activation and reduced anti-inflammatory effects, contributing to more effective infection control." (PMID 41586186, 2025). "It was observed that Sn and CD163 play a synergistic role in the ASFV infection process, which can explain why mAb 28C10 is able to block ASFV entry into PAMs." (PMID 40006922, 2025). "CD206 + IM are involved in response to wounding and infection recovery and CD163 + CD206 + monocyte-derived IM have been shown to directly derive from extravasating, circulating CD14 + monocytes in another human immune system-engrafted mouse model." (PMID 40920821, 2025). "Levamisole and 50 to 100 mg/kg of baicalin inhibited the CD163 protein expression level compared to the infection group (p < 0.001)." (PMID 40427615, 2025). "Levamisole and 25–100 mg/kg baicalin upregulated the mRNA expression of iNOS and CD86 and attenuated the levels of ARG1, IL-10, and CD163 in the spleen, in contrast with the infection group (p < 0.05)." (PMID 40427533, 2025). "To assess its role in PPMs’ susceptibility to PRRSV, we performed a receptor-blocking assay by pre-incubating the cells with a polyclonal antibody specific to CD163 before infection." (PMID 39723134, 2024). "After infection with S. epidermidis 1457, the proportion of CD163+ macrophages rose to 73 ± 4.2%, while the percentage of CD36+ cells declined to 12.79 ± 2.01%." (PMID 39567551, 2024). "PRRSV infection in PPMs was dependent on CD163, as pretreatment with an anti-CD163 antibody significantly reduced infection." (PMID 39723134, 2024). "Next, we further analyzed the DEGs in dMφ subsets (TNF+dMφ, CD86+dMφ, CD163+dMφ, and TGFβ+dMφ) after infection." (PMID 38730500, 2024). "While interactions with other receptors facilitate infection, it is been stablished the interaction with CD163 is necessary for the infection, as confirmed by studies involving genetically modified pigs lacking specific CD163 domains." (PMID 39434120, 2024).